NEK1 (NIMA related kinase 1)
Description:
Phosphorylates serines and threonines, but also appears to possess tyrosine kinase activity. Involved in DNA damage checkpoint control and for proper DNA damage repair. In response to injury that includes DNA damage, NEK1 phosphorylates VDAC1 to limit mitochondrial cell death. May be implicated in the control of meiosis (By similarity). Involved in cilium assembly.
Synonyms: KIAA1901; NY-REN-55; ALS24; OFD2; SRPS2; SRPS2A; SRTD6
Tractability: Small molecule: a structure with a bound ligand is known; a high-quality ligand is known; it belongs to a druggable protein family. PROTAC: it is named in the literature on targeted protein degradation; ubiquitination databases record sites on it; its protein half-life has been measured; a small molecule that binds it is known.
Target class: Other protein kinase NEK family; Kinase; Enzyme; Other protein kinase group; Protein Kinase
Gene: Protein-coding gene on chromosome 4 (169,369,704 to 169,612,644, reverse strand). Ensembl gene ENSG00000137601.
Subcellular location: Nucleus; Cytoplasm, cytoskeleton, microtubule organizing center, centrosome; Cytoplasm
Subcellular location (Human Protein Atlas): Nucleoplasm; Centriolar satellite; Cytosol; Primary cilium
Pathways (Reactome):
Metabolism: Regulation of pyruvate metabolism
Gene Ontology:
Molecular function: kinase activity; protein binding; protein kinase activity; protein serine kinase activity; 14-3-3 protein binding; ATP binding; protein serine/threonine kinase activity
Biological process: cilium assembly; protein phosphorylation; regulation of DNA damage checkpoint
Cellular component: centriolar satellite; centrosome; cytoplasm; cytosol; nucleoplasm; nucleus; pericentriolar material
Genetic constraint (gnomAD): Loss-of-function variants: 83 observed, 103.87 expected, observed/expected ratio (o/e) 0.8, 90% interval 0.67 to 0.96. The upper end of that interval is the gene's LOEUF score, 0.96, which puts it in group 4 of 6, group 1 being the genes least tolerant of losing a copy. Missense variants: 922 observed, 1,000.1 expected, observed/expected ratio (o/e) 0.92, 90% interval 0.87 to 0.97. Synonymous variants: 350 observed, 337.24 expected, observed/expected ratio (o/e) 1.04, 90% interval 0.95 to 1.13.
Homologues: Orthologues: chimpanzee NEK1 (99% identical), macaque NEK1 (98% identical), dog NEK1 (87% identical), rabbit NEK1 (87% identical), guinea pig NEK1 (86% identical), mouse Nek1 (82% identical), pig NEK1 (79% identical), rat Nek1 (76% identical), tropical clawed frog nek1 (55% identical), zebrafish nek1 (35% identical), Drosophila melanogaster lic (3% identical), Caenorhabditis elegans sek-4 (3% identical), and 2 more. Paralogues in human: MAP3K4 (13% identical), MAP3K3 (9% identical), MAP3K2 (8% identical), MAP2K5 (5% identical), MAP2K7 (5% identical), MAP2K1 (5% identical), MAP2K2 (4% identical), MAP2K4 (4% identical).
Diseases named in the same sentence as NEK1 in open-access papers:
NEK1 is named in the same sentence as 88 diseases in open-access papers, as found by Europe PMC text mining. Sharing a sentence is not in itself a finding about the gene and the disease. The quoted sentences say what the papers report.
amyotrophic lateral sclerosis (22 papers, 2017 to 2026). Amyotrophic lateral sclerosis (ALS) is a neurodegenerative disease characterized by progressive muscular paralysis reflecting degeneration of motor neurons in the primary motor cortex, corticospinal tracts, brainstem and spinal cord. "The NEK1 kinase controls ciliogenesis, mitosis, and DNA repair, and NEK1 mutations cause human diseases including axial spondylometaphyseal dysplasia and amyotrophic lateral sclerosis." (PMID 37188479, 2023). "Dysfunctions of NEK1 have been associated with the development and progression of Amyotrophic Lateral Sclerosis (ALS), Polycystic Kidney Disease (PKD), and cancers such as neural gliomas, Wilms’ tumor, prostate cancer, and thyroid cancer." (PMID 37046733, 2023). "Loss-of-function variants in NIMA-related kinase 1 (NEK1) constitute a major genetic cause of amyotrophic lateral sclerosis (ALS), accounting for 2 to 3% of all cases." (PMID 37585529, 2023). "The disease most strongly associated with NEK1 mutations is amyotrophic lateral sclerosis (ALS), a form of motor neuron disease with symptoms that do not overlap with SMD or short-rib polydactyly syndrome." (PMID 37188479, 2023). "Loss of function mutations of Nek1 have been identified in 3% of amyotrophic lateral sclerosis (ALS) patients." (PMID 35409400, 2022). "In the context of other human diseases, NEK1 was found to be involved in the development of amyotrophic lateral sclerosis (ALS), a neurodegenerative disorder that causes the death of motoneurons (MN)." (PMID 33673578, 2021). "NEK1 shows pleiotropic functions and has been found to be mutated in cancer cells, ciliopathies such as the polycystic kidney disease, as well as in the genetic diseases short-rib thoracic dysplasia, Mohr-syndrome and amyotrophic lateral sclerosis." (PMID 28710492, 2017). "For instance, mutations in NEK1 have now been implicated in amyotrophic lateral sclerosis (ALS), Parkinson’s disease (PD), hereditary spastic paraplegia (HSP), and cerebellar ataxia, underscoring its multifaceted role in neuronal homeostasis." (PMID 41154634, 2025). "Studies on amyotrophic lateral sclerosis (ALS) patients have linked the NEK1 gene to multiple cellular functions, including ciliogenesis, the DNA damage response (DDR), microtubule stability, neuronal morphology, and axonal polarity." (PMID 40731814, 2025). "Research has linked NEK1 to several human diseases, including polycystic kidney disease, amyotrophic lateral sclerosis (ALS), glioma, Wilms tumor, thyroid cancer, and prostate cancer." (PMID 40731814, 2025). "Mutation of NEK1 has been associated with polycystic kidney disease and amyotrophic lateral sclerosis (ALS)." (PMID 37835513, 2023). "In the last few years, different studies highlighted a significant enrichment of NEK1 loss of function (LoF) variants in amyotrophic lateral sclerosis (ALS), and an additional role for the p.Arg261His missense variant in the disease susceptibility." (PMID 35495032, 2022). "NIMA-related kinase 1 (NEK1), a gene encoding a serine/threonine kinase involved in cell cycle regulation, has been identified as a risk gene for amyotrophic lateral sclerosis (ALS)." (PMID 40389989, 2025). "Nek1 loss-of-function mutants confer susceptibility to amyotrophic lateral sclerosis (ALS)." (PMID 38534317, 2024). "Loss of function mutation of NEK1 leads to DNA damage accumulation in the motorneurons that may lead to several neurodegenerative diseases such as amyotrophic lateral sclerosis (ALS)." (PMID 33297404, 2020). "For instance, the loss-of-function mutations in the NIMA-Related Kinase 1 (NEK1) gene, which encodes a serine/threonine kinase, are involved in human developmental disorders and amyotrophic lateral sclerosis (ALS)." (PMID 37501215, 2023).
amyotrophic lateral sclerosis (continued). "Many genes have been linked to amyotrophic lateral sclerosis (ALS), including never in mitosis A (NIMA)‐related kinase 1 (NEK1), a serine/threonine kinase that plays a key role in several cellular functions, such as DNA damage response and cell cycle regulation." (PMID 38986433, 2025). "Limited copy number variations studies in amyotrophic lateral sclerosis: While CNVs in genes such as NEK1, TBK1, and C9orf72 have been linked to ALS, comprehensive, genome-wide CNV investigations are lacking." (PMID 40819305, 2026).
polycystic kidney disease (18 papers, 2007 to 2025). A usually autosomal dominant and less frequently autosomal recessive genetic disorder characterized by the presence of numerous cysts in the kidneys leading to end-stage renal failure. "NEK1 is associated with primary cilia and centrosomes, which was reported to be implicated in the development of polycystic kidney disease (PKD) when there is a NEK1 deficiency." (PMID 33297404, 2020). "Mutation in Nek1 and Nek8 genes are related to polycystic kidney disease, Nek6 overexpression is observed in hepatocellular carcinomas, and studies also show that Nek6 and Nek1 are related to DNA damage checkpoints." (PMID 25591119, 2015). "Two murine models of polycystic kidney disease, the so-called kidneys-anemia-testes (kat and kat2J) mice, have been linked genetically to the locus encoding Nek1 protein kinase." (PMID 25030234, 2014). "Nek8, like NEK1, has been linked genetically with a form of polycystic kidney disease; it localizes to the primary cilium of each cell where it functions to anchor mitotic centrosomes." (PMID 21214959, 2011). "Mutations in Nek1 (NIMA-Related Kinase 1) are causal in the murine models of polycystic kidney disease kat and kat2J." (PMID 18533026, 2008). "Of the mammalian Neks, both Nek1 and Nek8 were unexpectedly implicated in cilia function when it was found that mutations in laboratory mouse models of polycystic kidney disease (PKD) mapped to the Nek1 and Nek8 genes." (PMID 17727698, 2007). "For example, NEK1 mutations have been found in human patients with autosomal recessive Majewski type short-rib polydactyly syndrome, which is associated with polycystic kidneys, lethal skeletal dysplasia, polydactyly, facial dysmorphism, drastic growth defects in utero, and microcephaly." (PMID 37188479, 2023). "Furthermore, Nek1-deficient mice (kat and kat2j) display symptoms typically associated with ciliopathies, diseases caused by ciliary defects, including polycystic kidney disease." (PMID 37188479, 2023). "Mutations in Nek1 induce anemia, polycystic kidney and infertility." (PMID 28982183, 2017). "NEK1 deficiency causes early abnormalities in kidney development, including excessive apoptosis and diminished proliferation, and has been associated with polycystic kidney disease." (PMID 26317783, 2015). "Such a series of events may begin to explain how Nek1 deficiency leads to polycystic kidney disease in mice, through a mechanism that involves accelerated and aberrant apoptosis in the setting of endogenous or acquired DNA and cellular damage." (PMID 25030234, 2014). "Loss of function mutations in NEK1 are causal in the case of the murine polycystic kidney disease model lines KAT and KAT2J and one of the key features of the polycystic kidney diseases is aberrant cell proliferation." (PMID 31906878, 2020). "In this respect, the polycystic kidney disease that develops in kat2J/Nek1 −/− mice is much like human autosomal dominant PKD, in which cysts can form from all parts of the nephron." (PMID 25030234, 2014). "Nek1 is a centrosome-associated protein and mice without functional Nek1 develop polycystic kidneys." (PMID 18533026, 2008). "NEK1 and CTNNB1, together with AXIN1, GSK3B and TSC2, participate in the Wnt signaling pathway in urological cancer cells and polycystic kidney disease (PKD)." (PMID 26317783, 2015). "Nek1-deficient mice develop facial dysmorphism, male sterility, and slowly progressing polycystic kidney disease (PKD), with renal pathology similar to that of human autosomal dominant polycystic kidney disease (ADPKD), because Nek1 functions in the formation of primary cilia." (PMID 35299232, 2022). "In vivo, NEK1 -/- kat2J mice develop polycystic kidney disease at a young age and often do not survive past 3 weeks after birth (unpublished result)." (PMID 21214959, 2011).
polycystic kidney disease (continued). "The recent demonstration that Nek1 interacts with and phosphorylates TAZ, an adaptor protein in the E3 ubiquitin ligase complex, to modulate PC2 protein level provides another potential mechanism by which Nek1 inactivation may lead to polycystic kidney disease." (PMID 25030234, 2014).
ciliopathy (12 papers, 2013 to 2025). A genetic disorder of the cellular cilia or the cilia anchoring structures, the basal bodies, or of ciliary function. "Like the ciliopathies discussed previously, NEK1 association with C21orf2 links DNA repair proficiency to ciliary signaling axes, highlighting a complex signaling hub that underpins both tumor growth and potential radiosensitization strategies." (PMID 41154634, 2025). "In line with a prominent role of NEK1 in ciliogenesis, homozygous NEK1 mutations cause a perinatally fatal ciliopathy known as short rib-polydactyly syndrome type II (SRPS II)." (PMID 37585529, 2023). "Inactivation of NEK1 was recently associated with the human ciliopathy autosomal-recessive short-rib polydactyly syndrome." (PMID 23628112, 2013). "Beyond its roles in neurodegenerative diseases and ciliopathies, NEK1 has also been implicated in various cancers, where it appears to exert a dual function promoting tumorigenesis on one hand while offering a potential avenue for radiosensitization on the other." (PMID 41154634, 2025). "It was shown that NEK1, a causative gene of ciliopathy, was required in regulating cell cycle." (PMID 37901396, 2023). "Patients with mutations in NEK1, a DNA damage response gene mutated in patients with the ciliopathy short rib polydactyly syndrome, could potentially be treated in this manner." (PMID 30915099, 2019). "Furthermore, we identify the kinase Nek1, another ciliopathy-associated protein, as a potential binding partner of this array." (PMID 28017521, 2017). "Clinically, recessive NEK1 variants, such as G145R and L253S, have been identified in oral–facial–digital syndrome type II and short-rib thoracic dysplasia, directly linking NEK1 dysfunction to human ciliopathies and highlighting its conserved role in developmental signaling and tissue homeostasis." (PMID 41154634, 2025). "Mutations in Nek1 resulting in ciliopathies cause short rib polydactyl syndromes (SRPS), and Nek1 overexpression has been found to be a potential oncotarget for various cancers (i.e., prostate, glioma)." (PMID 35409400, 2022). "Genetic mutation in Nek1 was highly associated with short-rib polydactyly syndrome Type Majewski, a new ciliopathy, and Nek1 is localized to the basal body region." (PMID 25139956, 2014). "Mouse models affecting either NEK1 or NEK8 protein function show phenotypic overlap with ciliopathies." (PMID 23628112, 2013). "NEK1 interacts with other ciliopathy proteins C21orf2 and SPATA7, suggesting that other ciliopathies could likewise be treated with CDK inhibitors." (PMID 30915099, 2019).
glioma (11 papers, 2020 to 2025). A benign or malignant brain and spinal cord tumor that arises from glial cells (astrocytes, oligodendrocytes, ependymal cells). "Up-regulation of Nek1 in glioma tissue correlated with the clinical grade and Karnofsky performance scale, and was significantly associated with a poor OS, while an siRNA-mediated KD of Nek1 sensitized glioblastoma cells to the drug temozolomide." (PMID 32429458, 2020). "Our study was designed and conducted with a conclusion premised upon the notion that silencing LINC00883 could enhance the negative regulation of NEK1 by miR-136 and effectively reduce the malignant tumor characteristics of glioma, while reducing the risk of drug resistance." (PMID 35083134, 2021). "For instance, NEK1 overexpression has been observed in several malignancies, including gliomas, where its expression level correlates with tumor grade and poor patient prognosis." (PMID 41154634, 2025). "As for the NEK1 function in cancer, several publications reported overexpression of NEK1 in renal cell carcinoma and gliomas." (PMID 37835513, 2023). "Still, further studies with specimens from glioma-diagnosed patients are needed to confirm the clinical application of the LINC00883/miR-136/NEK1 axis in treating glioma." (PMID 35083134, 2021). "Hereby, we aim to explore the role of LINC00883 as a regulator of miR-136 and its target, NIMA-related kinase 1 (NEK1), thus, its involvement in the drug resistance of glioma cells." (PMID 35083134, 2021). "For exploring the effect of LINC00883, miR-136, and NEK1 on drug resistance in glioma, we conducted a series of cell experiments." (PMID 35083134, 2021). "Previously, Zhu and colleagues demonstrated that NEK1 is upregulated in glioma and correlated with the proliferation marker (Ki-67), tumour grade and patients’ poor survival." (PMID 31906878, 2020). "To test this hypothesis, we analyzed the effects of LINC00883/miR-136/NEK1 on glioma cell resistance to temozolomide (TMZ) and tumorigenicity in the in vitro and in vivo settings." (PMID 35083134, 2021). "Furthermore, knockdown of NEK1 by siRNA inhibited glioma cell growth and increased susceptibility to temozolomide (TMZ), the main chemotherapeutic drug used to treat glioma, leading to apoptosis." (PMID 32294979, 2020). "Together, these results suggest an important role of NEK1 in human gliomas and TMZ resistance." (PMID 32294979, 2020). "In glioma cells, NEK1 drives proliferation and survival through a multifaceted DDR network in which TLK1 phosphorylates NEK1 on T141, fostering its interaction with the ATR–ATRIP complex and priming ATR autophosphorylation at T1989 for efficient CHK1 activation." (PMID 41154634, 2025). "In human glioma tissue Nek1 expression was significantly up-regulated as compared to non-cancerous tissue and correlated with tumor grading and poor survival." (PMID 32429458, 2020). "Furthermore, the results of RT-qPCR suggested higher expression of LINC00883 and NEK1 yet poorer miR-136 expression in glioma tissues than in normal brain tissues." (PMID 35083134, 2021).
prostate carcinoma (6 papers, 2012 to 2025). A carcinoma that arises from epithelial cells of the prostate gland. "NEK1 may play an oncogenic function in prostate cancer through the phosphorylation of YAP." (PMID 37835513, 2023). "NEK1 haploinsufficient TRAMP mice display reduced YAP1 expression and, if castrated, fail to progress to overt prostate carcinomas, even while displaying reduced E-Cadherin (E-Cad) expression in hyperplastic ductules." (PMID 36979713, 2023).
renal cell carcinoma (4 papers, 2014 to 2023). "Nek1 is further reported to be associated with a decreased sensitivity to DNA damaging agents in renal cell carcinomas and to be part of a 12-gene tumor signature to predict progression of non-invasive to muscle-invasive bladder cancer." (PMID 32429458, 2020). "On the other hand, increased NEK1 expression is associated to a decreased sensitivity to treatment of damaged DNA in renal cell carcinoma." (PMID 26317783, 2015).
breast cancer (3 papers, 2016 to 2022). A primary or metastatic malignant neoplasm involving the breast. "In the UALCAN analysis, we discovered that NEK1/2/3/4/5/6/7/8/9/11 were statistically significantly overexpressed in breast cancer compared to normal tissues." (PMID 34834441, 2021). "Differences in expressions of NEK1/2/3/4/5/6/7/8/9/11 were statistically significant (p < 0.05) between normal and breast cancer tissues." (PMID 34834441, 2021). "This study found significant differences between normal and breast cancer tissues, and we determined that differences in NEK1/2/3/5/6/7/8/9/10 expressions were statistically significant at p < 0.001." (PMID 34834441, 2021). "Previous research demonstrated that NEK1 regulated bladder, kidney, and breast cancer progression." (PMID 34834441, 2021). "In the TIMER database, we found that NEK1/2/3/5/6/7/8/9/10 had significant p values < 0.001, and in the CCLE analysis, we also found overexpression levels of NEK gene family members in breast cancer cell lines." (PMID 34834441, 2021). "To prioritize non-mesenchymal genes for further investigation, we determined how the expression of FAT2, SNCA, CPNE8, NEK1 and CA12 correlated with ΔNp63α mRNA levels in breast cancer patient tumors analyzed by TCGA." (PMID 27081041, 2016).